SFRP1 (secreted frizzled related protein 1)
Diseases named in the same sentence as SFRP1 in open-access papers (continued):
Sharing a sentence is not in itself a finding about the gene and the disease.
breast carcinoma (continued). "However, given the body of literature linking Wnt signaling to breast cancer, we measured the expression of Axin2 in mammary tissue of control and Sfrp1-/- mice fed a ND or HFD because it is a direct readout of Wnt signaling." (PMID 24339864, 2013). "The most significant association was with sFRP1, where decreased expression predicts early recurrence in ER+ve breast cancer, most likely due to lack of Wnt inhibition." (PMID 23861811, 2013). "In addition, we observed associations between CDH13, SFRP1, and RASSF1A methylation and breast cancer subtypes and between SFRP1 methylation and patient's age." (PMID 22701537, 2012). "The Wnt negative regulator sFRP-1 is reduced or lost in 80% of breast carcinomas." (PMID 21767405, 2011). "Our study suggests that loss of SFRP1 allows non-malignant cells to acquire characteristics associated with breast cancer cells." (PMID 19422694, 2009). "Indeed, sFRP1 has also been shown to impact on transforming properties of breast cancer cells and cervix cancer cells; while sFRP2 has been shown to block proliferation of gastric cancer cells." (PMID 19473496, 2009). "That SFRP1 is located in a chromosomal region that is frequently deleted in breast cancer (8p12–p11.1) suggests that SFRP1 may also play a tumour suppressor role during mammary tumorigenesis." (PMID 18283316, 2008). "Conversely, SFRP1 knockdown enhanced breast cancer cell growth." (PMID 18283316, 2008). "In contrast to an adverse prognostic value of SFRP1 or SFRP5 methylation in breast cancer, failure of SFRP2 methylation as a prognostic biomarker may be explained by redundant functions of these closely related SFRP molecules." (PMID 18990230, 2008). "Similarly, SFRP1 sensitizes breast cancer cells to proapoptotic stimuli and SFRP3 suppresses tumor growth and cell invasion in prostate cancer cells." (PMID 18382662, 2008). "In breast cancer, frequent methylation and silencing of SFRP1 was recently documented; however, altered expression of other Wnt antagonist genes is largely unknown." (PMID 18283316, 2008). "To test whether the silencing of SFRP expression provides a growth advantage to breast cancer cells, we examined the effect of using siRNA (siSFRP1) to disrupt SFRP1 expression." (PMID 18283316, 2008). "Moreover, the down-regulation of SFRP1 has been observed in many tumors, including breast cancer, ovarian cancer, bladder cancer, mesothelioma, prostate cancer, colorectal cancer, and non-small cell lung cancers." (PMID 17626620, 2007). "One potential mechanism contributing to pathway activity might be loss of negative modulators of WNT signaling, as decreased expression of sFRP1 is well documented in human breast cancer." (PMID 17897439, 2007). "Our observations imply that targeting this interaction or the use of a 'ligand trap' like sFRP1 might be a valid approach to treat breast cancer by interfering with the canonical WNT pathway as well as the EGFR/ERK1/2 pathway." (PMID 17897439, 2007). "WNT antagonists may act as tumour suppressors and cause constitutive activation of WNT signalling when mutated; reduced expression of the secreted WNT inhibitors SFRP1 and WIF1 have been observed in breast cancers." (PMID 16933995, 2006). "Interestingly, we found that SFRP1 affects breast cancer independently of the Wnt signal pathway." (PMID 37963835, 2023). "Consequently, the PRECOG meta-Z-score for SFRP1 expression in breast cancer was −0.2, suggesting an absence of association between this gene’s expression and the patient’s outcome." (PMID 37190179, 2023). "A decreased level of SFRP1 protein was observed in the head and neck squamous cell carcinoma, cutaneous squamous cell carcinoma, and gastric cancer, while increased protein concentration was reported in basaloid oesophageal squamous cell carcinoma samples and breast cancer tissue specimens." (PMID 37999144, 2023).
breast carcinoma (continued). "Finally, the functional analysis indicated that SFRP1 might regulate the extracellular matrix to influence component and coagulation cascades, focal adhesion, protein export, and spliceosome pathways in breast cancer." (PMID 37963835, 2023). "On the other hand, the overexpression of SFRP1 in pre-invasive and invasive breast cancer cell lines induced a reduction in cell viability and migratory abilities, suggesting that SFRP1 could be a potential tool against breast cancer progression." (PMID 37190179, 2023). "Finally, we validated the co-expression profile of FMO2 and SFRP1 in 8246 patients with breast cancer with DNA microarrays data and 4421 patients with breast cancer with RNA-sequence data from bc-GenExMiner and 1284 patients with breast cancer with TCGA breast cancer data from UCSC Xena." (PMID 37963835, 2023). "In the present manuscript, we first corroborated previous studies from our group and others, in which a decrease in SFRP1 expression was observed in the continuum of breast cancer risk and in breast cancer, compared to non-tumoral tissue, by analyzing public datasets." (PMID 37190179, 2023). "By stratifying the TCGA cohort by the breast cancer molecular subtypes, we noticed that the SFRP1 promoter was more methylated in luminal lesions compared to normal tissue (p-value < 0.0001), which was coherent with SFRP1 decreased expression in luminal lesions compared to normal samples." (PMID 37190179, 2023). "We confirmed that the expression of KIF4A, UBE2C and COL11A1 was distinctly increased in BC specimens compared with normal breast specimens, while the expression of SFRP1, SAA1 and RBP4 was distinctly decreased in breast cancer specimens." (PMID 35646102, 2022). "Furthermore, sFRP1 has been demonstrated to be a potential biomarker in breast cancer survivors which support the notion that serological sFRP1 could be a potential biomarker for HCC." (PMID 30513115, 2018). "Increased expression of Wnt ligands was reported in breast cancer and dishevelled in cervical cancer, while decreased expression of dickkopf-1 was reported in pancreatic cancer, secreted frizzled-related protein 1 (SFRP1) in lung cancer, and WIF1 in cervical cancer." (PMID 27843945, 2016). "Additionally, SFRP1 re-expressing breast cancer cells revealed a reduced tumor outgrowth in vivo supporting the putative tumor suppressive role of SFRP1 although detailed mechanisms of SFRP1 function and its impact on Wnt signaling in dependency of different breast cancer subtypes are still lacking." (PMID 25036590, 2014). "Thus, an increased level of SFRP1 might sensitize triple negative breast cancer patients towards chemotherapy, thereby improving prognosis of this aggressive breast cancer subtype." (PMID 25033833, 2014). "To determine, whether BDNF, a potential novel target gene of the tumor suppressor SFRP1, may also mediate inhibiting effects on cell proliferation of breast cancer cells, we generated a stable BDNF over-expressing breast cancer in vitro model using BT20 breast cancer cells." (PMID 25036590, 2014). "Further investigations on the interaction of EpCAM with SFRP1 and TCF7L2 and on additional factors, which may be causal for changes upon EpCAM overexpression, will help to characterize unique molecular properties of EpCAM-positive breast cancer cells." (PMID 21281469, 2011). "The results presented in this paper showing that sFRP1-mediated WNT pathway blockade strongly blocks the in vivo tumor forming potential of MDA-MB-231 breast cancer cells suggest that interference with WNT signaling at the ligand-receptor level may be a valid therapeutic approach in breast cancer." (PMID 19473496, 2009). "Only MMP11, MYBL2, SFRP1, and UBE2C identified in our study are also featured together as biomarkers in the PAM50 breast cancer 50 gene panel." (PMID 39596491, 2024).
breast carcinoma (continued). "Women undergoing 12-week physical training after breast cancer treatment showed statistically significant reductions in serum DKK-1 and sFRP-1 concentrations." (PMID 38792313, 2024). "In addition, a few studies in mice depleted of Sfrp1 demonstrated that it negatively regulates mammary branching and the expression of ERα, raising the question of the causal role the lack of SFRP1 plays in luminal breast cancer development in women." (PMID 37190179, 2023). "Our studies demonstrated a decrease in stromal SFRP1 and SFRP2 expression in breast cancer stroma, with the lowest levels observed in IDC tissues." (PMID 37091166, 2023). "We also anticipate that an increase in SFRP1 expression in breast cancer cell lines should decrease cell viability and reduce ESR1 expression, at least in luminal breast cancer cell lines." (PMID 37190179, 2023). "Epigenetic silencing of WNT/β‐CATENIN antagonists is frequently observed in breast cancer, and reduced expression of APC, CDH1, SFRP1 and SFRP2 due to promoter hypermethylation has been reported in many breast tumours." (PMID 33462997, 2021). "Our independent analysis of primary ER+PIK3CA-mutant breast cancers, which exhibit high INPP4B expression, identified these and additional upregulated Wnt genes (LEF1, MYCN, FZD7, SFRP2, TCF7L1, CTNNB1, FZD4, and SFRP1)." (PMID 34035258, 2021). "For this, we induced EMT in BT474 (HER2-high breast cancer cells) by treating the cells with an EMT-inducing supplement cocktail (containing Wnt-5a, TGF-β1, anti-human E-Cadherin antibody, anti-human sFRP1 antibody, and anti-human Dkk1 antibody) for 15 days." (PMID 34575017, 2021). "In our study, we found that both ALDH1A1 and SFRP1, two commonly important genes for EMT and CSCs, are capable of predicting the overall survival rates for breast cancer." (PMID 33092068, 2020). "They discovered the interaction between NTR of SFRP1 and TSP1 disrupts the adhesion and migration of MDA-MB-231 breast cancer cell via α3β1 integrin." (PMID 32074995, 2020). "BRCA_M14.n8 includes the hub gene SFRP1 as well as EGFR and FOXC1, PAM50 classifier genes used to define basal breast cancer (online)." (PMID 30993001, 2019). "MYC was found to repress the WNT inhibitors DKK1 and SFRP1, leading to the activation of the WNT pathway in breast cancer cell lines." (PMID 31623618, 2019). "Re-expression of SFRP1 in an ERα-positive breast cancer cell line (MCF7), which has lost expression of the endogenous SFRP1 gene, had the opposite effect providing additional confirmation of an SFRP1-regulated gene network." (PMID 31248446, 2019). "A total of three has-miR-542-5p target mRNAs were closely related to overall survival of breast cancer patients in both KMPD and GEPIA, and these are: YWHAB, LY9, and SFRP1." (PMID 29371858, 2018). "Several Wnt/β-catenin antagonists were epigenetically repressed in breast cancer, including WIF1, SFRP1, SFRP2, SFRP5, DKK1, and DKK3." (PMID 28467796, 2017). "Secreted frizzled-related protein 1 (SFRP1) expression is down-regulated in a multitude of cancers, including breast cancer." (PMID 28687085, 2017). "The identified shRNAs target genes involved in signaling pathways known to regulate breast cancer stem cells, including WNT (SFRP1), CD44 (FKBPL), and the PI3K/AKT (FOXO3A) signaling pathways." (PMID 26595803, 2016). "Among the 340 under-expressed genes containing the 586 hyper-methylated CpGs, there were several tumor suppressor genes with under-expression that has previously been observed in breast cancer, such as L3MBTL4, ID4, RUNX3, PROX1, SFRP1 and others." (PMID 27386846, 2016). "Some genes, well-known in breast cancer subtyping and involved in the cancer-relevant pathways, are the hubs of the network, e.g., FOXQ1, SFRP1 and ESR1." (PMID 27786176, 2016).
breast carcinoma (continued). "Many members of this module, including WIF1, WNT1, SFRP1, FZD9, and FZD8 were hypermethylated and underexpressed in both luminal-A and luminal-B breast cancers but exhibiting larger deviations in DNAm and mRNA expression in the luminal-B subtype." (PMID 26664652, 2015). "Specifically, breast cancer cells overexpressed GINS2, TTK, CEP192, and shugoshin 1 and have lower levels of C-Nap1, semaphorin 6A, MDM2 and SFRP1." (PMID 25278993, 2014). "In summary we assessed that forced SFRP1 expression in BT20 and SKBR3 breast cancer cells leads to an induction of BDNF expression." (PMID 25036590, 2014). "We initially assessed promoter methylation of SFRP1, SFRP2, SFRP5, ITIH5, DKK3, and WIF1 in 112 paired breast cancer tissue and serum samples by using qualitative MSP." (PMID 23320751, 2013). "Down regulation of SFRP1, SFRP4 and 5 are reported in aggressive breast cancer, ovarian cancer and gastric cancer respectively." (PMID 23825088, 2013). "Up-regulation of Snail and Zeb2, along with repressed expression of Sfrp1, are features of EMT which contribute to mammary tumours." (PMID 23883065, 2013). "Both low SFRP1 and TCF7L2 levels have been described in a subset of breast carcinomas derived from infiltrating ductal carcinoma." (PMID 21281469, 2011). "Probably, the reduction of both SFRP1 and TCF7L2 is required to more potently enhance Wnt signaling in breast cancer cell lines, and a contribution of additional factors cannot be excluded." (PMID 21281469, 2011). "In sFRP1 knockdown breast cancer cell lines, EGFR is transactivated, indicating a synergistic effect of Wnt and EGFR signaling in breast cancer development." (PMID 20828404, 2010). "Included among the genes epigenetically silenced in breast cancer are genes involved in cell cycle regulation (p16INK4A, CCND2, RASSF1A), cell signaling (SFRP1, SFRP5), differentiation (HOXA9), immortalization (p57), and DNA repair (MGMT, BRCA1)." (PMID 19995452, 2009). "We have previously reported that expression of the Wnt antagonist genes SFRP1 and SFRP5 is frequently silenced by promoter hypermethylation in breast cancer." (PMID 18990230, 2008). "We initially used three breast cancer cell lines (MDA-MB-435S, MDA-MB-436 and MDA-MB-468) to assess the knockdown efficiency of our siSFRP1, which most effectively disrupted SFRP1 expression in MDA-MB-436 cells." (PMID 18283316, 2008). "For that reason, in the present study we initially evaluated the expression status of SFRP1, SFRP2 and SFRP5 in a panel of breast cancer cell lines." (PMID 18283316, 2008). "The genes include members of the family of secreted frizzled-related proteins (SFRP1 and SFRP2), which are frequently epigenetically inactivated during colon and breast cancer progression, and contribute to aberrant activation of Wnt signaling." (PMID 16596166, 2006). "What is the potential significance of stromal SFRP1 and SFRP2 expression in breast cancer?" (PMID 37091166, 2023). "As such, the reduced levels of stromal SFRP1 and SFRP2 in DCIS and IDC may facilitate WNT signaling and promote breast cancer growth, survival, invasion, or stem cell activity." (PMID 37091166, 2023). "Secondly, we found that FMO2 inhibits breast cancer through co-expression with SFRP1, and the latter plays a role through non-Wnt signal pathway, which is also not reported." (PMID 37963835, 2023). "As such, SFRP1 and SFRP2 expression in fibroblasts could serve to regulate breast cancer progression by acting on epithelial cells and other cells in the tumor microenvironment." (PMID 37091166, 2023). "Both luminal and basal breast cancer cell lines do not express any SFRP1 due to gene promoter hypermethylation." (PMID 36139547, 2022).
breast carcinoma (continued). "In our first HTS approach, we used SFRP1 as C2TSG, expressed in breast cancer cells." (PMID 36139547, 2022). "In breast cancer, reduction in WNT signaling by addition of secreted negative regulators of the pathways, like DKK1 or SFRP1 can promote reduction in migration and invasion, whereas inhibition of SFRP1, and thus elevated WNT signaling, can support an EMT phenotype and sensitize to TGFβ‐induced EMT." (PMID 34459003, 2021). "When we further tested the effect of SFRP1 expression in a panel of breast cancer cell lines, we found that SFRP1 reduced the mRNA levels of EGR2 in T47D cells but not in TMX2–28 cells (a Tamoxifen resistant variant of MCF7) or MDA-MB-231 cells." (PMID 28687085, 2017). "Secreted frizzled related protein 1 (SFRP1) functions as an important inhibitor of the Wnt pathway and is a known tumor suppressor gene, which is epigenetically silenced in a variety of tumors e.g. in breast cancer." (PMID 25036590, 2014). "This positive correlation in vitro may be maintained in vivo due to the tight correlation detected between SFRP1 and BDNF mRNA in human breast cancer samples." (PMID 25036590, 2014). "Therefore, we performed immunohistochemical staining of SFRP1 and BDNF on a breast cancer tissue microarray comprising 144 specimens." (PMID 25036590, 2014). "If concomitant DNA methylation of the RASSF1A and SFRP1 genes observed in vitro is biologically relevant in vivo, we reasoned that DNA methylation of these genes would also be present in breast cancer tissues, but not in normal breast cells or tissues." (PMID 19995452, 2009). "The apoptotic genes SPP1 and SFRP1 are candidate tumor suppressors for various cancers; AXL gene is a proto-oncogene, and NOL3 (ARC, apoptosis repressor with CARD domain) is induced in human breast cancer and confers chemo- and radiation-resistance." (PMID 19455236, 2007). "In summary, these results show that, in some breast cancer cell lines, both canonical and non-canonical Wnt signaling can be blocked by sFRP1 treatment." (PMID 17897439, 2007). "How might stromal SFRP1 and SFRP2 facilitate breast cancer progression?" (PMID 37091166, 2023). "Similarly, In the CPTAC database, SFRP1 was downregulated in breast cancer compared to healthy regardless of individual cancer stages, race, tumor histology, and major subclasses." (PMID 37963835, 2023). "However, this role of SFRP1 in mediating chemosensitivity in breast cancer was shown to be independent of its effect on Wnt signaling." (PMID 37533202, 2023). "In addition, we excavated secreted Frizzled-related protein 1 (SFRP1), a known negative regulator of the Wnt/β-catenin pathway, from the perspective of co-expression analysis to reveal the potential molecular mechanism of FMO2 in breast cancer." (PMID 37963835, 2023). "Furthermore, a secreted frizzled-related protein 1 (SFRP1) is known to be responsible for hyperplasia, and thus, lack of SFRP1 is accompanied by both tumor development and poor prognosis for breast cancer." (PMID 33092068, 2020). "Deletion of Sfrp1 in mice also resulted in enhanced estrogen-stimulated responses and occasional hyperplasias, but was not sufficient for the development of spontaneous mammary tumors." (PMID 31248446, 2019). "First, two human breast cancer cell lines lacking SFRP1 mRNA were selected to generate breast cancer in vitro models exhibiting forced SFRP1 re-expression: the basal-A breast cancer cell line BT20 and the luminal-like HER2-positive breast cancer cell line SKBR3." (PMID 25036590, 2014). "Indeed, a positive correlation between SFRP1 and BDNF protein expression could be shown (p<0.001) in primary breast cancer samples." (PMID 25036590, 2014). "When SFRP1 is knocked down in immortalized non-malignant mammary epithelial cells, the cells exhibit a malignant phenotype which resembles the characteristics observed in metastatic breast cancer stem-like cells." (PMID 22928951, 2012).